MIMT1 (MER1 repeat containing imprinted transcript 1)
Synonyms: MIM1; NCRNA00067; LINC00067
Gene: Long non-coding RNA gene on chromosome 19 (56,840,853 to 56,848,560, forward strand). Ensembl gene ENSG00000268654.
Diseases named in the same sentence as MIMT1 in open-access papers:
MIMT1 is named in the same sentence as 16 diseases in open-access papers, as found by Europe PMC text mining. Sharing a sentence is not in itself a finding about the gene and the disease. The quoted sentences say what the papers report.
Stillbirth (3 papers, 2010 to 2025). Death of the fetus in utero after at least 22 weeks of gestation. "In bovine, alteration in MIMT1 methylation has been associated with aberrant placental transcriptome and stillbirth." (PMID 40569608, 2025). "We herein describe the positional identification of a 110 kb microdeletion in the maternally imprinted PEG3 domain that results in a loss of paternal MIMT1 expression and causes late term abortion and stillbirth in cattle." (PMID 21152099, 2010). "This has been also demonstrated in the bovine lineage: a genomic deletion in the Usp29/Mimt1 region resulted in stillbirth in cows." (PMID 27327533, 2016).
tumour (1 paper, 2024). "Animal experiments further validated that MIMT1 knockdown inhibits tumour growth." (PMID 39091947, 2024). "Rescue experiments, clone formation and CCK-8 assays, were conducted to ascertain whether MIMT1 promotes tumour proliferation through FGF2." (PMID 39091947, 2024). "Furthermore, in vivo xenograft experiments demonstrated that MIMT1 knockdown suppressed tumour volume and weight." (PMID 39091947, 2024).
MIMT1 also shares sentences with these, for which no sentence is quoted: cancer (4 papers); melanoma (4); glioblastoma (2); leukemia (2); abortion (1); breast carcinoma (1); Holt-Oram syndrome (1); lymphoma (1); Metastatic disease (1); multiple myeloma (1); non-small cell lung carcinoma (1); ovarian carcinoma (1); retinoblastoma (1); triple-negative breast carcinoma (1).